FAP (fibroblast activation protein alpha)
Diseases named in the same sentence as FAP in open-access papers (continued):
Sharing a sentence is not in itself a finding about the gene and the disease.
cancer (continued). "This review summarizes current clinical evidence on Lutetium-177 ( 177 Lu)-FAP RLT in GEP cancers, including pancreatic, biliary, gastric, and colorectal malignancies." (PMID 42077585, 2026). "Our findings validate and extend our earlier results, where we demonstrated using the same dual‐marker FAP/αSMA IHC assay and Random Forest‐based machine learning model that stromal FAP is associated with both BCR‐free survival and cancer‐specific survival." (PMID 41410015, 2026). "Stromal FAP predicted cancer‐specific survival using both median (log‐rank test, p = 0.008) and upper quartile cut‐offs (p = 0.02)." (PMID 41410015, 2026). "PET/CT using 68Ga- or 18F-labeled inhibitors of FAP (FAPI), such as [68Ga]Ga-FAPI-46 or [18F]F-FAPI-74, can visualize these cancer-associated fibroblasts." (PMID 40647503, 2025). "FAP-positive CAFs in the stroma are known to be predictive of poor survival in many cancer types ranging from colon to lung cancer." (PMID 39868181, 2025). "This makes FAP a promising target for cancer therapy and potentially as a biomarker for immunotherapy treatment response." (PMID 40741380, 2025). "Imaging and intranuclear radiotherapy for FAP represent a promising strategy for the evaluation and treatment of malignant tumors." (PMID 40430845, 2025). "The substantial upregulation of FAP is considered a biomarker for CAFs, with potential as a unfavourable prognosis biomarker for various cancers." (PMID 39780187, 2025). "Fibroblast activation protein (FAP) has emerged as a highly promising molecular target for cancer theranostics, with current research prioritizing the optimization of FAP-targeted radiopharmaceutical pharmacokinetics." (PMID 40959258, 2025). "We identified three major stromal cell types, including cancer-associated fibroblasts (CAFS; FAP, COL1A1), perivascular-like cells (PVL; PDGFRA, PDGFRB), and endothelial cells (PECAM1, CD34)." (PMID 40858992, 2025). "Fibroblast activation protein (FAP) is a pan-cancer targetthatis useful for imaging, ideally all epithelial cancers." (PMID 39954291, 2025). "FAP concentrations increased in 10 (63%) and decreased in 6 cancer patients (38%), indicating variable FAP homeostasis in individual patients." (PMID 40690098, 2025). "We demonstrate that cancer patients have lower FAP concentrations as compared to healthy volunteers." (PMID 40690098, 2025). "FAP-targeted radioligand therapy appears to be a promising treatment option for patients with advanced cancer who have exhausted standard therapies." (PMID 41463267, 2025). "The potential therapeutic benefits of FAP inhibition further underscore the need for larger prospective studies to define its role in cancer treatment." (PMID 40283957, 2025). "Overexpression of FAP in cancer cells inhibits apoptosis and promotes proliferation and invasion of cancer cells, whereas downregulation of FAP expression decreases proliferation and invasion, promoting apoptosis." (PMID 40438601, 2025). "In this work, we developed and characterized Llama-derived Nbs targeting human FAP, a key cancer biomarker for diagnosis and therapy." (PMID 41460404, 2025). "To model cancer conditions relevantfor FAPα-targeted fluorescent contrast agents, we used HEK293Tet-Off cells with inducible FAPα expression." (PMID 40679920, 2025). "Secreted IL19, in turn, promotes cancer cell growth and acts in a paracrine manner on adjacent fibroblasts, enhancing their activation, as evidenced by the increased αSMA and FAPα expression." (PMID 40647365, 2025). "For optimal evaluation and treatment of malignant tumors, a promising strategy involves imaging and intranuclear radiation therapy targeting fibroblast activation protein-α (FAP)." (PMID 40430845, 2025). "Targeting FAP, either directly or by modulating its activity, has emerged as a promising strategy in cancer therapy." (PMID 41373408, 2025).
cancer (continued). "These radiotracers bind to FAP on CAFs and potentially eliminate cancer cells by irradiating the CAFs or through the crossfire effect on adjacent cancer cells." (PMID 40016527, 2025). "While FAP expression in the stroma has been established in several cancer types, its soluble form, sFAP, also holds considerable interest." (PMID 41373408, 2025). "Co-culturing studies with FAP+ cells demonstrate that the cancer cells exhibit increased proliferation and migration." (PMID 40438601, 2025). "Being involved in the extra-cellular matrix (ECM) tissue remodeling processes, FAP was found to be present also in such non-cancer disease like fibrosis, arthritis, atherosclerosis and infarction." (PMID 40762892, 2025). "Our results suggest that the combination of thermoplasmonic agents with anti‐FAP TMs with proven specific accumulation at FAP‐expressing sites pave the way to a new era of cancer theranostics for solid tumors." (PMID 40837037, 2025). "Agents targeting FAP, hypoxia, GRPr, and integrins are among those that have progressed furthest in clinical trials due to their excellent avidity for tumors and pan-cancer targeting properties, and are poised to enter clinical use soon." (PMID 40863874, 2025). "Additional clustering and dimensionality reduction, utilizing four marker genes (ACTA2, FAP, PDGFRB, and NOTCH3), resulted in the delineation of four cancer-associated fibroblast (CAF) subpopulations." (PMID 40589759, 2025). "The prepared nanoconjugates demonstrated excellent colloidal stability, protein immobilization capacity, and selective binding to FAP‐overexpressing cancer cells with minimal off‐target interactions observed in control groups." (PMID 40837037, 2025). "We measured FAP concentrations in plasma samples taken from patients before planned chest radiation for cancer therapy (n = 18, 12 men and 6 women) using the FAP ELISA." (PMID 40690098, 2025). "FAP is a surface serine protease that is upregulated in reactive stromal fibroblasts, and has been detected in 90% of cancers." (PMID 40433364, 2025). "FAP is a well-established and highly specific mediator of such processes, known for its pivotal role in tissue remodeling in cancer stroma and fibrotic diseases of the liver and lung." (PMID 40869127, 2025). "FAP contributes to resistance to neoadjuvant chemotherapy and poor prognosis by inducing mesenchymal transformation and cancer stem cell transformation." (PMID 40438601, 2025). "Early clinical trials of radiolabelled FAP ligands for the treatment of FAP-expressing cancers indicate that they are well tolerated." (PMID 41049848, 2025). "By addressing these challenges, targeting FAP-positive CAFs holds the promise of crafting more nuanced and potent strategies in cancer therapy." (PMID 40741380, 2025). "Fibroblast activation protein alpha (FAP) is a serine protease that is expressed at basal levels in benign tissues but is overexpressed in a variety of pathologies, including cancer." (PMID 40542914, 2025). "Previous efforts to target FAP+ CAFs in malignant tumors have been extensive, with numerous clinical trials conducted." (PMID 40855046, 2025). "These expression profiles makes FAP an attractive target for cancer research, diagnosis and treatment, particularly in the development of theranostic radiopharmaceuticals." (PMID 40000459, 2025). "In contrast, FAP has been gaining a spotlight as a promising radiopharmaceutical theranostic or therapeutic target for cancer." (PMID 40293537, 2025). "Targeted radionuclide therapy (TRT) is a type of cancer therapy, and radionuclide therapy targeting FAP is a hot topic of current research." (PMID 40244052, 2025). "Numerous approaches have been developed to bolster immunity against FAP-expressing cells, notably CAFs, and to curb cancer proliferation." (PMID 40313969, 2025). "The growing body of evidence for several FAPI derivatives has underscored the potential of FAP as a novel pan-cancer imaging target." (PMID 40473461, 2025).
cancer (continued). "Currently, targeted imaging of FAP and FAP-targeted therapy, are gaining tremendous interest in cancer and inflammatory diseases." (PMID 40084998, 2025). "In the field of theranostics, over the last 10 years the pan-cancer biomarker Fibroblast Activation Protein (FAP) has gained increasing attention." (PMID 40762892, 2025). "We sought to develop a multifunctional probe targeting FAP, a prominent biomarker for a broad variety of cancer entities." (PMID 41348275, 2025). "For example, fibroblast activation protein (FAP), highly expressed in CAFs across various cancer types but minimally expressed under normal conditions, has emerged as a promising target." (PMID 40248695, 2025). "In intestinal-type GC, FAP is expressed more strongly in the endothelial cells, stroma, and moderately differentiated cancer cells compared to GC of diffuse type (mostly in endothelial cells, cells of cancer with limited cellular connections)." (PMID 41244835, 2025). "In cancer imaging, small-molecule FAP inhibitor (FAPI) PET/CT has demonstrated superior sensitivity for detecting primary tumors and metastases." (PMID 40607439, 2025). "In summary, the imaging targets for CAFs in cancer diagnosis and treatment mainly focus on FAP, including PET/CT, fluorescence imaging, and other modalities." (PMID 40656546, 2025). "FAP-directed therapies have demonstrated objective responses in patients with advanced, treatment-refractory cancers." (PMID 40647503, 2025). "FAP has been recently attracting interest since its involvement in angiogenesis, growth, aggressiveness, progression, and prognosis of cancer." (PMID 40762892, 2025). "Immunohistochemical analysis confirmed that the majority of spindle-shaped cells express fibroblast activation protein (FAP) and α-smooth muscle actin (α-SMA), identifying them as cancer-associated fibroblasts (CAFs)." (PMID 41153834, 2025). "Fibroblast activation protein (FAP) is a serine protease that is present in activated fibroblasts in cancer and other disease states, such as pulmonary fibrosis." (PMID 40863874, 2025). "The humanized murine anti-FAP monoclonal antibody F19, known as Sibrotuzumab, showed a specific FAP targeting effect in cancer patients." (PMID 39780187, 2025). "A significant study employing a transgenic mouse model engineered to express the diphtheria toxin receptor under the FAP promoter demonstrated that depletion of FAP+ CAFs via diphtheria toxin enhanced the efficacy of anti-cancer vaccines." (PMID 40313969, 2025). "In a Phase I trial, 177Lu-FAPI-46 was administered to 18 patients with advanced, treatment-refractory FAP positive cancers, achieving stable disease in two-thirds of cases with minimal radiation to healthy tissues." (PMID 41441395, 2025). "Given the extent to which the TME hinders the efficacy of immunotherapies, targeting FAP +ve CAFs in this manner makes this a viable combination candidate for immunotherapies against particularly immune-cold OC cancers with high stromal content." (PMID 40379112, 2025). "FAP has long been a target for cancer therapy, but the development of FAP targeted radioligands has led to an increased interest in imaging FAP for assessment of cancer and other diseases." (PMID 39572227, 2025). "Further research with larger cohorts and longer follow-up periods is needed to better understand the role of FAP in cancer and response to radiation injury." (PMID 40690098, 2025). "To analyze changes of FAP concentrations due to radiation effects, we measured FAP concentrations in plasma samples from the same cancer patients after finalization of chest radiation therapy." (PMID 40690098, 2025). "Diagnostically, the FAPI has suboptimal specificity for detecting malignant tumors, and interindividual variability in FAP expression complicates its widespread use." (PMID 39857102, 2025).
cancer (continued). "2-Phosphorylpyrrolidines can act as fibroblast activation protein alpha (FAPα) inhibitors, increased content of which is observed in 90% of carcinomas and which is interesting as a target for cancer therapy." (PMID 40732343, 2025). "More studies are required to study and confirm FAP as a potential biomarker for immunotherapy response in various types of cancer." (PMID 40741380, 2025). "These outcomes correlate with significantly higher patient-reported satisfaction scores (p < 0.01), positioning 177Lu-FAP-2286 as a transformative theranostic agent for FAP-expressing cancers." (PMID 40725089, 2025). "Accordingly, FAP inhibitor (FAPI) has been developed, and FAP-based PET tracer have shown promise for imaging a wide range of malignant tumors." (PMID 41345810, 2025). "Future studies with larger cohorts and extended follow-up are necessary to confirm our findings and evaluate the utility of circulating FAP as a biomarker in cancer patients post-radiation." (PMID 40690098, 2025). "A single-cell transcriptomics analysis (TISCH2 database) revealed that TNFRSF12A is highly expressed in cancer-associated fibroblasts (CAFs) and positively correlated with CAF markers (FAP: ρ = 0.304; PDPN: ρ = 0.364)." (PMID 41300305, 2025). "FAP is an attractive target for molecular imaging for cancer as it is minimally expressed in normal tissues hence is a perfect target for theranostics." (PMID 40741380, 2025). "Baseline FAP concentrations were significantly lower in cancer patients (median 91 ng/mL, 25th-75th percentiles 72–123 ng/mL) compared to healthy controls (median 118 ng/mL, 25th-75th percentiles 104–140 ng/mL, P = 0.0002)." (PMID 40690098, 2025). "The tracer demonstrated high and reliable uptake rates in primary cancers, binding to human FAP at sub‐nanomolar concentrations; due to its low molecular weight, the tracer accumulated rapidly and displayed low immunogenicity." (PMID 40656546, 2025). "Fibroblast activation protein (FAP), a serine protease expressed on cell surface, is highly upregulated in over 90% of epithelial carcinomas." (PMID 39963103, 2025). "Clinical investigations involving first-generation FAP-targeting antibodies have provided novel insights by demonstrating the feasibility of modifying FAP-specific cancer targeting through the conjugation of toxins or chelators with FAP-specific antibodies." (PMID 38543239, 2024). "This transformative effect ultimately fuels cancer progression, thereby underscoring FAP as a promising target for cancer therapeutic intervention." (PMID 38826849, 2024). "One area of research with much recent interest is the use of FAP inhibitors (FAPi) as a PET imaging agent in cancer patients whose tumors or TME express FAP more highly than those in mice." (PMID 38275890, 2024). "Within this scope, the present review aims to provide a comprehensive examination of the biological rationale for targeting FAP in cancer imaging and therapy." (PMID 39765634, 2024). "were the first to show that ACT therapy targeting FAP effectively suppresses the proliferation of FAP-expressing cancer cells within the peritoneal cavity in murine models." (PMID 39421736, 2024). "Fibroblast activation protein (FAP) is a type II transmembrane serine protease that has emerged as a promising target in various cancer types due to its overexpression in several malignancies, specifically epithelial cancers." (PMID 39335703, 2024). "The studies presented herein demonstrate the efficacy of FAP as a cancer-specific marker and highlight the potential of FAP and other CAF markers as targets for antibody-conjugated therapies or immune-adjuncts." (PMID 39335130, 2024). "FAP has been shown to be expressed on cancer cells themselves, which increases the likelihood of these proteins effectively targeting cancer." (PMID 39335130, 2024). "Consistent with previous reports, we observed the expression of FAP in several murine cancer models and chose it as a CAF target for NIR-PIT." (PMID 38275890, 2024).
cancer (continued). "Benefiting from minimal expression in normal tissues but excessive expression in epithelial tumors, FAP is an attractive target for cancer theranostics." (PMID 38646648, 2024). "FAP has been identified to play a role in cancer by modifying the bioactive signaling peptides through their enzymatic activity." (PMID 39579201, 2024). "FAP is predominantly expressed in pathological conditions such as fibrosis and cancer, making it a compelling target." (PMID 39335703, 2024). "In cervical lesions, it has been reported that FAP increases significantly in advanced premalignant lesions and cancer." (PMID 38606999, 2024). "Recently, there has been a steady rise in clinical research focusing on the use of fibroblast activation protein (FAP)-targeted PET imaging in various cancer types." (PMID 39061653, 2024). "We first measured the expression of genes involved in adipocyte differentiation (PPAR-γ, AP2, HSL, Adiponectin, Leptin), cancer-associated fibroblast (CAF) markers (LIF, FAP, α-SMA), and inflammation (IL-6, IL-8, IL-1β, CXCL-10, TNF-α)." (PMID 39072314, 2024). "The patients considered here had cancer at both primary and metastatic sites which were scorable for FAP expression (n = 77)." (PMID 39335130, 2024). "Concurrent KEGG analysis supported the significant downregulation of pathways associated with ECM-receptor interactions, focal adhesions, PI3K-Akt signaling, proteoglycans in cancer, and IL-17 signaling post-FAP ablation." (PMID 38826849, 2024). "We used CD31, a marker of endothelial cells, and FAP, expressed by activated fibroblasts, to study angiogenesis and stroma formation in human cancer tissues." (PMID 39022761, 2024). "Along this trajectory, FAP-targeted positron emission tomography (PET), utilizing FAP inhibitors (FAPi) labeled with positron emitters, has gained traction as a powerful imaging approach in both cancer and inflammation." (PMID 38695960, 2024). "[68Ga]Ga-Pentixafor and [68Ga]Ga-FAPI-4 are gaining prominence for the diagnosis of overexpressed Chemokine Receptor-4 (CXCR4) and Fibroblast Activation Protein (FAP) receptor, respectively, in the microenvironment of numerous cancer types." (PMID 39050235, 2024). "Overall, our findings are consistent with the evolving paradigm highlighting the crucial role of stromal cells, including FAP+ fibroblasts, in chronic inflammation and cancers across various organs such as the liver, lung, heart, and joints." (PMID 39042469, 2024). "Elevated FAP expression has been identified in activated fibroblasts and stromal fibroblast-like cells in numerous human diseases and cancers." (PMID 39056788, 2024). "The results indicated that while glucose uptake and hypoxia were similar between cancer cells alone and in combination with PSCs, a specific marker of fibrosis (FAPα) was significantly higher in PSC-rich environments." (PMID 39410013, 2024). "Fibroblast activation protein (FAP), predominantly expressed by CAFs, has emerged as a promising target in both cancer diagnostics and therapeutics." (PMID 39765634, 2024). "By deconvoluting spatial transcriptomics, we characterized different cell niches composed of specific FAP+ CAF clusters, associated with immuno-protective or immuno-suppressive cells, enriched either in endothelial or cancer cells." (PMID 38561380, 2024). "FAP is a serine protease with overexpression on CAFs in more than 90% of human cancer, which not only takes part in ECM remodeling, but also induces the immunosuppressive microenvironment." (PMID 38644492, 2024). "The co-expressed genes of FAP across cancers were then shortlisted with genes having a Pearson correlation coefficient > 0.5 (Online Resource 2)." (PMID 39579201, 2024). "FAP is minimally expressed by fibroblasts in the resting state but is highly upregulated by CAFs in cancer as well as other fibroproliferative diseases (e.g., idiopathic pulmonary fibrosis, hepatic fibrosis, rheumatoid arthritis, and myocardial infarction)." (PMID 38275890, 2024).